FGF2 (fibroblast growth factor 2)
Diseases named in the same sentence as FGF2 in open-access papers (continued):
Sharing a sentence is not in itself a finding about the gene and the disease.
asthma (continued). "Recently, fibroblast growth factor 2 (FGF2) has been reported to be an inflammatory regulator; however, its role in asthma remains elusive." (PMID 35093168, 2022). "A recent review summarized the role of FGF2 as an immunomodulatory factor in COPD and severe asthma." (PMID 34136479, 2021). "It is also interesting to note that there were two studies of in vivo mouse models of acute asthma and COPD which showed that recombinant FGF2 (rFGF2) is protective against airway inflammation and lung function, rather than enhancing inflammation." (PMID 32300593, 2020). "Interestingly, it has been shown that FGF2 can be released from those inflammatory cells including T lymphocytes, eosinophils, mast cells, macrophages, and myeloid dendritic cells, which might partly explain the elevated FGF2 expression in the BALF of asthma patients after allergen stimulation." (PMID 32300593, 2020). "Moreover, FGF2 levels in the sputum could be a biomarker for asthma severity in light of the correlation of its levels with lung function, implicating its role in airway hyperresponsiveness, the main feature of asthma." (PMID 32300593, 2020). "Fibroblast growth factor (FGF)-2 and platelet-derived growth factor (PDGF)-BB also have a significant role in airway remodeling in asthma." (PMID 23731974, 2013). "Furthermore, we found that Lrp1 knockdown significantly reduced the levels of FGF2 and phosphorylated ERK compared with NC shRNA treatment in the tracheal tissues of mice with OVA-induced asthma, consistent with our in vitro findings." (PMID 40338656, 2025). "Although the characterisation of FGF2 expression in asthma samples provides first-hand clues for the potential role of FGF2 in disease conditions, it has not been systemically studied prior to this study." (PMID 35093168, 2022). "Taken together, our findings indicated that exosomal miR-221-3p derived from BMSCs inhibited FGF2 expression and the ERK1/2 signaling, thus attenuating proliferation, migration, and ECM deposition in ASMCs and alleviating asthma progression in OVA-induced asthmatic mice." (PMID 35990834, 2022). "Although this possibility in immune cells in asthma was not explored, co-localisation of FGF2 in airway or vascular infiltrated inflammatory cells was observed." (PMID 35093168, 2022). "ECs are key immunomodulatory cells in airway diseases, but the involvement of FGF2 in the dysfunction of ECs in asthma and COPD patients has not been well studied yet." (PMID 32300593, 2020). "Furthermore, FGF-2 is known to contribute to HASMC proliferation and migration ability that are believed to be major contributors to airway remodeling in asthma." (PMID 22529962, 2012). "FGF2 elevation within bronchial areas is not surprising, considering the potential of FGF2 to be a pro-fibrotic factor that plays a role in subepithelial fibrosis in patients with asthma." (PMID 35093168, 2022). "Therefore, in this study, a chronic mouse asthma model induced by the house dust mite (HDM), one of the main allergens inducing allergic asthma, was applied to investigate the potential immunomodulatory role of FGF2 in asthma patients." (PMID 35093168, 2022). "Nevertheless, the expression pattern of FGF2, that is, the expression levels and cellular locations of the FGF2 protein in asthmatic lungs, has not been fully investigated, as well as the role of FGF2 in modulating chronic airway inflammation in patients with asthma." (PMID 35093168, 2022). "Finally, the role of FGF2 in regulating immune cells and other airway resident cells, such as ASMs and fibroblasts, which are critical players in modulating airway inflammation in asthma, were not investigated." (PMID 35093168, 2022). "Moreover, intranasal administration of budesonide, a clinical medicine to treat asthma, was unable to suppress FGF2 overexpression in HDM-induced asthmatic mouse lungs, which might explain the clinical evidence of the correlation between FGF2 expression levels and asthma severity." (PMID 35093168, 2022).
asthma (continued). "In non-diabetic individuals with asthma, MCP-1 levels correlated with IL-1β, IL-1RA, MDC/CCL-22, IP-10/CXCL-10, GM-CSF, FGF-2, PDGF-AA, PDGF-BB, and HbA1c." (PMID 27709105, 2015).
cardiac hypertrophy (35 papers, 2011 to 2025). "It was found that Lo-FGF2 significantly reduced myocardial cell death and increased the regeneration of small vessels, while the application of Hi-FGF2 caused cardiac hypertrophy." (PMID 36102060, 2022). "Intramyocardial injection of FGF2 (plus heparin) in rats with hypertension-induced cardiac hypertrophy was associated with significant improvements in systolic pump function and ventricular dilation, as well as increased myocardial capillary density." (PMID 30895179, 2019). "Mice with systemic FGF2 deficiency developed less severe cardiac hypertrophy in response to aortic banding in line with the role of FGF2 as cardiomyocyte growth factor, whereas cardiac angiogenesis was not evaluated in this study." (PMID 30895179, 2019). "FGF-2-deficient mice developed significantly less cardiac hypertrophy in response to transverse aortic coarctation." (PMID 29776409, 2018). "In this study both male and female animals were treated with Iso, known to cause cardiac hypertrophy and fibrosis in mice, in order to discern sex-specific pathologies associated with the deletion of specific FGF2 isoforms." (PMID 24244869, 2013). "Interestingly, some of these targets such as Tgfb1, Hras, Fgf2, and Ppargc1a have been implicated in cardiac hypertrophy suggesting that low-dose dasatinib indeed impacts genes that affect heart growth and remodeling." (PMID 33689087, 2022). "A recent study on a mouse model, has shown that FGF16 prevents angiotensin II-induced cardiac hypertrophy and fibrosis by antagonizing FGF2." (PMID 40843168, 2025). "CFs-associated FGF2 and FGF16 contribute to cardiac hypertrophy via stimulating CMs in a paracrine fashion." (PMID 40843168, 2025). "FGF16 also plays a role in cardiac hypertrophy, though the role is the opposite of FGF2 in cardiac hypertrophic remodeling." (PMID 39452290, 2024). "FGF2 is crucial for in vitro myocardial remodeling, and the FGF2-FGF receptor-1 axis is a potential therapeutic target for treating cardiac hypertrophy." (PMID 38355415, 2024). "Animal models have shown that FGF2 is important for the manifestation of cardiac hypertrophy, whereas COL4A1 is involved in extracellular matrix organization, which has been linked with atherogenesis." (PMID 38576084, 2024). "FGF2 can promote cardiac hypertrophy and fibrosis through its high-molecular-weight FGF2 isoform (hi-FGF2)." (PMID 38355415, 2024). "ERK as the most prominent downstream effector of FGF-2 signaling plays a predominant role in the development of both physiological and pathological cardiac hypertrophy." (PMID 37443814, 2023). "In the past, several in vitro studies revealed evidence for an important role of FGF-2 in cardiac hypertrophy." (PMID 37443814, 2023). "In conclusion, these data imply that Hi-FGF-2 is a contributor to cardiac hypertrophy, fibrosis, and heart failure, while Lo-FGF-2 seems to exert opposite functions as a component of adaptive responses in the injured myocardium." (PMID 37443814, 2023). "Noteworthy, FGF-2 exists as an isoform with a high molecular weight (Hi-FGF-2) and low molecular weight (Lo-FGF-2), thus it is important to determine the potential effects of both in the context of cardiac hypertrophy and tissue remodeling." (PMID 37443814, 2023). "For example, presumably through activation of FGFR1, the paracrine factor FGF2 promotes cardiac hypertrophy under conditions of excess catecholamine stimulation and renin-angiotensin system activation." (PMID 35513431, 2022). "The presented results demonstrate that FGF2 is the main stimulating component of the growth of myocardial hypertrophy." (PMID 34204341, 2021). "For example, thyroxine, a potent stimulator of cardiac hypertrophy and vascularization, has been shown to enhance FGF2 expression and increase cardiac capillary endothelial cell proliferation and angiogenesis." (PMID 34204341, 2021).
cardiac hypertrophy (continued). "The L-NAME + FGF2 group showed the presence of minimal cardiac hypertrophy and slight nuclear degenerative changes and in liver, and there was congestion of the centrilobular vein and slight dilatation of the sinusoidal vein." (PMID 33959027, 2021). "FGF signaling is known to play a pathophysiological role in the heart as evidenced by worsened cardiac hypertrophy in isoproterenol stimulated hearts of FGF2 transgenic mice." (PMID 33281625, 2020). "It was reported that there was no remarkable loss of cardiac function when blood pressure was decreased in FGF2 knockout mice; however, a crucial reduction in cardiac hypertrophy was observed with aortic coarctation." (PMID 32848793, 2020). "FGF2 KO mice were protected against cardiac hypertrophy and fibrosis following isoproterenol stimulation." (PMID 33281625, 2020). "Studies also revealed differential effects of high and low molecular weight isoforms of FGF2 on cardiac hypertrophy, fibrosis and inflammation." (PMID 30895179, 2019). "For example, thyroxine, a potent stimulus of cardiac hypertrophy and vascularization, was shown to upregulate the expression of FGF2 and to increase cardiac capillary endothelial cell proliferation and angiogenesis." (PMID 30895179, 2019). "FGF2 has been shown to mediate cardiac hypertrophy in response to multiple stimuli including pressure overload, angiotensin II, and isoproterenol." (PMID 25626875, 2015). "Fgf16 has been described to prevent cardiac hypertrophy and fibrosis by competing with Fgf2 for the binding site of the FGF receptor 1c, Fgfr1c, in a paracrine manner." (PMID 25333065, 2014). "Although Fgf2 is broadly expressed in mice, hypertension-induced cardiac hypertrophy and fibrosis are less developed in Fgf2 knockout mice, indicating that Fgf2 promotes them." (PMID 23600527, 2013). "Fibroblast growth factor 2 (FGF2) mediates cardiac hypertrophy, cardiac fibrosis, and protection against cardiac injury, and is made in high molecular weight and low molecular weight isoforms (Hi FGF2 and Lo FGF2, respectively)." (PMID 24244869, 2013). "An upregulation of FGF2 mRNA was also measured in human patients presenting with ventricular hypertrophy." (PMID 24244869, 2013). "FGF2 promotes cardiac hypertrophy and fibrosis by activating MAPK signaling through the activation of FGF receptor (FGFR) 1c." (PMID 24046748, 2013). "In mouse models of cardiac hypertrophy that are induced by pressure overload or adrenergic overstimulation, there is a marked upregulation of Fgf2 mRNA." (PMID 24244869, 2013). "Similarly, the conditional deletion of FGF2 results in decreased cardiac hypertrophy induced by ischemic injury, delayed wound healing and increased bone mineralization, while Postn has been linked to cardiac issues, wound healing and bone regeneration." (PMID 34809697, 2021). "Now, many TNF-dependent genes linked to ECM remodeling as well as AF are upregulated with exercise in WT atria compared to sedentary, including Mmp14, Fgf2 (i.e., fibroblast growth factor 2, which activates p38 and induces cardiac hypertrophy as well as fibrosis), Gsk3β, and Tln1." (PMID 33424629, 2020). "Whether up-regulation of FGF2 in the heart due to pressure overload-induced cardiac hypertrophy after TAC is also responsible for the induction of cardiac FGF23, and if so, the role of cardiac FGF23 in this setting has to be further elucidated." (PMID 29892269, 2018). "FGF-2 was reported to induce cardiac hypertrophy through activation of FGF receptor 1 (FGFR1)." (PMID 29776409, 2018). "Moreover, we also compared the expression of β-MHC, which is upregulated in cardiac hypertrophy, and found that FGF-2 (25 ng/mL for 48 h)-induced β-MHC mRNA upregulation was significantly attenuated in calcitriol (10 nM)-treated HL-1 cells." (PMID 29776409, 2018). "However, FGF-2 is essential for the development of pressure overload- or angiotensin II-induced cardiac hypertrophy." (PMID 29776409, 2018).
cardiac hypertrophy (continued). "FGF2 mainly promotes cardiac hypertrophy and cardiac fibrosis." (PMID 28824452, 2017). "While FGF16 and FGF21 may prevent cardiac hypertrophy and fibrosis, FGF2 and FGF23 display the opposite effect." (PMID 27184924, 2016). "2K1C-induced cardiac hypertrophy and fibrosis is also protected against in FGF2 knockout mice." (PMID 27803896, 2016). "Isoproterenol-induced cardiac hypertrophy is also protected against in FGF2 knockout mice." (PMID 27803896, 2016). "In addition, FGF2 is upregulated in the heart during various forms of cardiac pathology including ischemic damage and cardiac hypertrophy." (PMID 25626875, 2015). "Isoproterenol-induced cardiac hypertrophy was shown to be protected in Fgf2 knockout mice." (PMID 24046748, 2013). "FGF16 may prevent cardiac hypertrophy and fibrosis by competing with FGF2 for the binding site of FGFR1c in a paracrine manner." (PMID 24046748, 2013). "However, cardiac hypertrophy and fibrosis were less developed in Fgf2 knockout mice with myocardial infarcts." (PMID 24046748, 2013). "Consistent with reports Lo-FGF-2 alters the gene profile of contractile proteins from “adult” to “fetal” programs when added to cultured neonatal cardiomyocytes, a distinct characteristic that is attributed to pressure overload-induced cardiac hypertrophy in vivo." (PMID 37443814, 2023). "Neonatal and adult cardiac fibroblasts mainly express the high-molecular weight isoform of FGF2, which is stimulated and secreted through angiotensin II treatment, thereby acting on cardiac myocytes via induction of a fetal gene program resulting in cardiac hypertrophy." (PMID 29892269, 2018). "Furthermore, isoproterenol-induced cardiac hypertrophy was protected in Fgf2 knockout mice." (PMID 23600527, 2013). "Accumulation of fibroblast growth factor 2 (FGF-2) has been shown to exacerbate cardiac hypertrophy, and we demonstrated that DOX treatment increased the expression of FGF-2." (PMID 32354131, 2020). "FGF-2-null mouse models demonstrated that FGF-2, secreted by cardiac non-myocytes, mediated the development of cardiac hypertrophy in response to pressure overload or elevated Angiotensin II levels." (PMID 24827991, 2014). "The exaggerated cardiac hypertrophy and fibrosis observed in a mouse model subjected to pressure overload correlated with significantly elevated cardiac Hi-FGF-2 levels, pointing to Hi-, rather than Lo-FGF-2 as an agent of pathological change." (PMID 24827991, 2014). "In addition, it was shown that hemodynamic stress, rather than FGF2 and myocardial hypertrophy, correlates with switching of the studied isoforms." (PMID 34204341, 2021). "However, neither spironolactone treatment nor FGF23 knockout alters the induction of FGF2 in the high blood pressure-induced cardiac hypertrophy through TAC." (PMID 29892269, 2018). "However, 2K1C-induced cardiac hypertrophy and fibrosis did not develop in Fgf2 knockout mice." (PMID 24046748, 2013).
multiple myeloma (35 papers, 2004 to 2025). "Mesenchymal stem cells (MSCs) play a crucial role in angiogenesis associated with multiple myeloma, mainly by secreting pro-angiogenic factors like vascular endothelial growth factor (VEGF) and fibroblast growth factor 2 (FGF2)." (PMID 40140850, 2025). "We performed a nested case–control study using prospective samples from the Janus Serum Bank in Norway to investigate associations between multiple myeloma risk and prediagnostic serum levels of MCP-3, MIP-1α, FGF-2, VEGF, fractalkine, and TGF-α." (PMID 40152768, 2025). "To reliably identify associations between blood immune marker levels of MCP-3, MIP-1α, FGF-2, VEGF, fractalkine, and TGF-α and the future risk of multiple myeloma, we performed a case–control study using prospective samples from the Janus Serum Bank in Norway." (PMID 40152768, 2025). "For example, soluble CD138 is shown to inhibit the mitogenicity of fibroblast growth factor 2, decrease the growth of carcinoma cells, and induce apoptosis in myeloma cells in vitro." (PMID 34364875, 2021). "In multiple myeloma, stromal-derived IL-6 stimulates FGF2 expression in tumor cells, which in turn stimulates the secretion of IL-6." (PMID 27007053, 2016). "Serum SDC1 and bFGF/FGF2 levels were elevated in multiple myeloma patients before treatment compared to the control group." (PMID 26293675, 2015). "In the present study, we examined the role of IRES-mediated regulation of FGF-2 translation in tumorigenesis as a critical step not only in solid tumors but also in multiple myeloma." (PMID 25053990, 2014). "Using prospective samples obtained 8 years (median) before multiple myeloma diagnosis, Hofmann and colleagues did not observe associations between multiple myeloma risk and serum levels of FGF-2, VEGF, and TGF-α." (PMID 40152768, 2025). "Thus, myeloma cells produce FGF2 that stimulates the production of IL-6 by BMSCs that in turn promotes FGF2 secretion by MM cells, finally creating a loop of stimulation between tumor and stromal cells." (PMID 39482742, 2024). "Importantly, myeloma cells seem to be the predominant source of FGF2 within the BM, and FGF2 secretion plays a pivotal role not only in autocrine stimulation but also in mediating paracrine stimulation between tumor and stromal cells." (PMID 39482742, 2024). "Additionally, IL-6 stimulation upregulates FGF2 secretion in keratinocytes, myeloma cells, and basal cells through the IL-6/STAT3 pathway." (PMID 38338991, 2024). "In addition, IL-6 and FGF2 together can enhance proliferation of myeloma cells." (PMID 27007053, 2016). "Myeloma cells secrete angiogenic factors such as VEGF, hepatocyte growth factor (HGF), fibroblast growth factor-2 (FGF-2), and insulin like growth factor-1 (IGF-1), thereby enhancing cell proliferation and survival." (PMID 41471085, 2025). "In multiple myeloma (MM), PTX3 affects in vitro and in vivo fibroblast growth factor 2-mediated MM angiogenesis, promoting cytotoxicity in MM cells by inhibiting the cross-talk between plasma cells, endothelial cells and fibroblasts." (PMID 36362114, 2022). "Formononetin has been found to suppress fibroblast growth factor 2 (FGF2)-induced STAT3 activation, successfully suppressing multiple myeloma, leukemia, lymphoma and solid tumors that display constitutive STAT3 activation." (PMID 31052435, 2019). "It has recently been demonstrated that the forced expression of HOXB7 in multiple myeloma induces the up-regulation of VEGFA, FGF2, MMP2 and PDGFA, and the down-regulation of thrombospondin 2, a profile largely shared by RC." (PMID 25115389, 2014). "In addition, we observed a decline in the levels of MCP-3, FGF-2, VEGF, fractalkine, and TGF-α in multiple myeloma cases over time, possibly indicating multiple myeloma progression." (PMID 40152768, 2025). "Interestingly, myeloma macrophages also secrete proangiogenic factors such as vascular endothelial growth factor (VEGF), IL-8, and fibroblast growth factor-2 (FGF-2)." (PMID 38213954, 2023).
multiple myeloma (continued). "Moreover, the tumor microenvironment releases growth factors for myeloma cells including HGF, matrix metalloproteinases (MMPs), fibroblast growth factor-2, MCP-1 (monocyte chemotactic protein-1), and others." (PMID 27764795, 2016). "In some ways, the co-upregulation of FGF2 and SDC1 seen in tissue biopsies and PBL (albeit at the mRNA level) of PO NS-cHL patients in our study may be related to certain features of multiple myeloma." (PMID 23988031, 2013).